IL11RA (interleukin 11 receptor subunit alpha)
Diseases named in the same sentence as IL11RA in open-access papers (continued):
Sharing a sentence is not in itself a finding about the gene and the disease.
bladder cancer (1 paper, 2025). "Based on existing studies and the results of this study, we speculate that IL11RA may influence the development of bladder cancer." (PMID 40755754, 2025). "Finally, intersecting these key genes with risk-consistent genes yielded eight immune-related genes that were negatively associated with bladder cancer risk: LIMS2, TP53INP2, IRAK3, STX2, CYP27A1, IL11RA, KCNMB1, and PDLIM7." (PMID 40755754, 2025). "Differential expression analysis revealed that, compared to the normal bladder cell line SV, the expression levels of LIMS2, IL11RA, KCNMB1, and PDLIM7 were significantly downregulated in all three bladder cancer cell lines (5637, T24, and HT1376)." (PMID 40755754, 2025). "Subsequent box plot analysis further demonstrated significantly lower expression of six genes (LIMS2, IRAK3, STX2, IL11RA, KCNMB1, and PDLIM7) in bladder cancer cell lines, consistent with bioinformatics analysis." (PMID 40755754, 2025). "Although there are currently no direct clinical interventions targeting IL11RA, its potential value in predicting the efficacy of targeted therapy for bladder cancer warrants further investigation." (PMID 40755754, 2025). "In vitro qRT-PCR validation in bladder cancer cell lines showed downregulation of LIMS2, IRAK3, STX2, IL11RA, KCNMB1, and PDLIM7, consistent with bioinformatics findings, suggesting that these genes may serve as potential therapeutic targets." (PMID 40755754, 2025). "Through integrated multi-omics analysis and experimental validation, six genes, LIMS2, IRAK3, STX2, IL11RA, KCNMB1, and PDLIM7, were selected as potential immune-related biomarkers for bladder cancer, providing promising biomarkers and therapeutic targets for personalized treatment." (PMID 40755754, 2025). "The consistent downregulation of these genes in bladder cancer tissues was further validated using independent public datasets, and qRT-PCR experiments confirmed the differential expression of the following six genes: LIMS2, IRAK3, STX2, IL11RA, KCNMB1, and PDLIM7." (PMID 40755754, 2025).
bladder tumor (1 paper, 2025). "Combined with immune infiltration analysis, IL11RA expression was found to be significantly negatively correlated with the increased infiltration of naive B cells and activated dendritic cells in tumor tissues, suggesting that IL11RA may regulate the bladder tumor immune microenvironment." (PMID 40755754, 2025).
chondrosarcoma (1 paper, 2024). A malignant cartilaginous matrix-producing mesenchymal neoplasm arising from the bone and soft tissue. "In addition, IL-11 stimulation led to enhanced cell motility in chondrosarcoma tumour cells, and knockdown of either IL-11Rα or GP130 in these cells significantly reduced migration." (PMID 38248304, 2024).
chronic lung disease (1 paper, 2022). According to the definitions of the American and British Thoracic Societies, including pulmonary functional tests, X-rays, and CT scans for items such as fibrosis, bronchiectasis, bullae, emphysema, nodular or lymphomatous abnormalities. "Using control, IPF and IPF with PH lungs from human and PH animal models, we showed for the first time that IL-11/IL-11Rα may be implicated in the development of PH associated to IPF chronic lung disease." (PMID 36376885, 2022).
chronic pancreatitis (1 paper, 2022). A chronic inflammatory process causing damage and fibrosis of the pancreatic parenchyma. "Our analysis of human pancreatic tissues, although limited, revealed that IL11 and IL11RA are increased in chronic pancreatitis." (PMID 35408908, 2022). "We investigated the expression of IL11 and IL11RA in human pancreatitis by performing immunostaining for IL11 and IL11RA in pancreatic tissue sections from patients with chronic pancreatitis and from a control individual." (PMID 35408908, 2022). "In mice, IL11 was increased in the pancreas after pancreatic duct ligation, and in humans, IL11 and IL11RA levels were elevated in chronic pancreatitis." (PMID 35408908, 2022).
colorectal tumours (1 paper, 2010). "Furthermore, IL11 and IL11Rα expression correlate with invasion and proliferation in human gastric and colorectal tumours." (PMID 20553623, 2010).
endometrial tumour (1 paper, 2017). "IL11 protein and mRNA, along with IL11Rα protein levels are progressively increased with increased endometrial tumour grade, which is in line with findings in other tumour types such as ovarian and colorectal." (PMID 28186993, 2017). "In conclusion, IL11 has comprehensively emerged as an important factor stimulating epithelial endometrial tumour progression and IL11Rα inhibition may offer a new strategy for novel therapeutic development." (PMID 28186993, 2017).
gastric adenocarcinoma (1 paper, 2018). "Some primary gastric adenocarcinoma samples (19.1%) were found to have an increased copy number of IL11RA." (PMID 29507648, 2018).
gastric adenoma (1 paper, 2019). A neoplastic polyp that arises from the stomach. "In this model, gastric adenomas spontaneously and reproducibly develop with 100% penetrance in 4‐week‐old mice with an absolute genetic dependence on bi‐allelic expression of the il11rα and Stat3 genes, but completely independent of IL6 signaling." (PMID 30885958, 2019).
Giardia infections (1 paper, 2022). "Several cytokine receptors are differentially expressed during the Giardia infections, including IL11RA, IFNGR1, IFNGR2, IL10RA, and ACKR3." (PMID 35573800, 2022).
leukaemia (1 paper, 2024). "Unsurprisingly, IL-11Rα expression was also found to be increased in leukaemia and lymphoma, among other cancers." (PMID 38248304, 2024).
liver fibrosis (1 paper, 2025). "In vivo experiments on liver fibrosis have confirmed that blocking IL11Rα with a specific antibody effectively inhibits fibrosis." (PMID 40018034, 2025).
Obesity (1 paper, 2020). Accumulation of substantial excess body fat. "We found IL11RA and IL17RB were downregulated, IL19 and IL25 were upregulated in obesity group compared with normal group." (PMID 33197880, 2020).
osteomyelitis (1 paper, 2022). An acute or chronic inflammation of the bone and its structures due to infection with pyogenic bacteria. "The expression of 2 interleukin-related genes was significantly different, among which IL11RA was highly expressed in gene cluster A osteomyelitis." (PMID 36544487, 2022). "The expression of 1 interleukin-related gene was significantly different, with IL11RA being highly expressed in cluster A osteomyelitis." (PMID 36544487, 2022). "The expression of 2 interleukin-related genes was significantly different, with IL11RA and IL17RA highly expressed in cluster B osteomyelitis." (PMID 36544487, 2022). "The expression of 2 interleukin-related genes were significantly different, among which IL11RA and IL17RA were highly expressed in gene cluster B osteomyelitis." (PMID 36544487, 2022). "The differences between IL11RA and IL17RA in the m6A cluster and gene cluster suggested that the two genes may be involved in osteomyelitis-mediated inflammation." (PMID 36544487, 2022).
pancreatitis (1 paper, 2022). Inflammation of the pancreas. "In therapeutic studies, we examined the potential of a neutralising IL11RA antibody to treat pancreatitis." (PMID 35408908, 2022). "We test the therapeutic potential of a neutralising IL11RA antibody for the prevention of PSC activation in vitro and fibrosis in the pancreatic duct ligation (PDL) mouse model of pancreatitis in vivo." (PMID 35408908, 2022). "Pancreatitis factors, including TGFβ, CTGF and PDGF, induced IL11 secretion from PSCs and a neutralising IL11RA antibody prevented PSC activation by these stimuli." (PMID 35408908, 2022).
pneumonia (1 paper, 2019). An acute, acute and chronic, or chronic inflammation focally or diffusely affecting the lung parenchyma, caused by an infection in one or both of the lungs (by bacteria, viruses, fungi, or mycoplasma.). "However, IL-11Rα mRNA levels were unchanged during pneumonia, suggesting that IL-11 signaling capacity is unlikely a function of receptor density." (PMID 31415618, 2019).
proliferative diabetic retinopathy (1 paper, 2024). Advanced retinopathy due to diabetes mellitus characterized by the formation of new vessels in the retina. "In vitreous samples from proliferative diabetic retinopathy (PDR) patients, elevated levels of IL-11Rα, but not IL-11, were detected." (PMID 39294742, 2024).
pulmonary hypertension (1 paper, 2022). Increased pressure within the pulmonary circulation due to lung or heart disorder. "This work introduce IL-11 and IL-11Rα as a drivers of pulmonary hypertension potentially druggable to reduce pulmonary artery remodeling." (PMID 36376885, 2022).
Thrombocytopenia (1 paper, 2017). A reduction in the number of circulating thrombocytes. "A possible side effect of blocking IL11Rα in cancers in humans, is the effect on platelet counts, since IL11 is used as a treatment option for thrombocytopenia after chemotherapy." (PMID 28186993, 2017).
tumor (26 papers, 2007 to 2025). "Additionally, IL11 and IL11Rα overexpression are associated with tumour progression, growth and differentiation and poor prognosis in colorectal, gastric, hepatocellular and breast cancers." (PMID 28186993, 2017). "Similar findings have been reported in non-small cell lung cancer (NSCLC), where IL11RA also demonstrated tumor-suppressor activity, and its expression level was negatively correlated with NSCLC risk." (PMID 40755754, 2025). "The liposomes encapsulated with cisplatin-loaded mesoporous MnO2 target tumor cells through surface-modified IL11Rα." (PMID 39897587, 2025). "IL‐11 mutein binds to the IL‐11R/gp130 complex and blocks IL‐11/IL‐11RA signal transduction, reducing the tumour growth." (PMID 40673604, 2025). "The IL‐11/IL‐11RA signalling pathway and tumour proliferation were significantly down‐regulated as assessed by IHC staining of pSTAT3, and cyclin D1 and Ki67, respectively." (PMID 40673604, 2025). "IL11RA is associated with T cells CD8 and can inhibit tumor growth, enhance drug resistance, and has potential immunomodulatory effects, improving survival outcomes." (PMID 39558952, 2024). "This relationship allowed us to demonstrate that either silencing IL-11Rα or debilitating the PRC2 complex through EZH2 inhibition can reduce primary tumor growth and prevent lung metastatic growth in vivo." (PMID 38886296, 2024). "In that study, the addition of a Smo agonist also induced STAT3 activation, while removal of STAT3 from the mouse epidermis or disruption of IL‐11Ra/STAT3 signaling significantly reduced SmoM2‐driven tumor development." (PMID 34482626, 2022). "We found that the IL-11+ cells in tumor tissues were mostly fibroblasts and a few epithelial cells and that deletion of Il11ra or Il11 attenuated CAC development in mice." (PMID 33863879, 2021). "A positive correlation between the expression of IL-11Rα in tumour cells and bone metastasis incidence was reported in advanced breast cancer patients." (PMID 34201209, 2021). "To directly determine the effect of activated STAT3 signaling on tumor growth we next stably transfected the IL-11Rα subunit into DLD-1 and SW48 CRC cells." (PMID 30572654, 2018). "Combination treatment enhanced survival before the tumours approached maximum tumour volume at 22 days, versus 13 days for the IgG control group, or 15 days for IL11Rα Ab alone and doxorubicin alone treatment groups." (PMID 28186993, 2017). "Activated pSTAT3 was evident in tumours treated with IgG control or doxorubicin alone, but levels were significantly reduced in the epithelial cells of tumours treated with IL11Rα Ab alone or in combination with doxorubicin." (PMID 28186993, 2017). "Combination IL11Rα Ab treatment with doxorubicin significantly reduced tumour growth 15 days after the commencement of treatment versus all other treatment groups (466.3 mm3 ± 136) (p < 0.05)." (PMID 28186993, 2017). "Mice with subcutaneous AN3CA xenograft tumours were administered with IgG control, IL11Rα Ab alone, or in combination with doxorubicin, or doxorubicin alone and tumour volume calculated." (PMID 28186993, 2017). "Semi-quantitation of cleaved-caspase-3 immunostained tumour tissue sections indicated a significant increased in tumour epithelial cell apoptosis in response to IL11Rα Ab or doxorubicin treatment alone (p < 0.01) compared to IgG control." (PMID 28186993, 2017). "Hematoxylin and eosin staining showed areas of tissue necrosis in AN3CA subcutaneous tumour tissues treated with IL11Rα Ab alone or in combination with doxorubicin." (PMID 28186993, 2017). "Strong staining for both IL11 and IL11Rα was identified in tumour vascular endothelial and smooth muscle cells as recently reported." (PMID 20553623, 2010). "IL11Rα immunostaining intensity was increased in cancer epithelium in the Grades 1 and 2 tumours compared to epithelium from postmenopausal women." (PMID 20553623, 2010).
tumor (continued). "IL11Rα protein was upregulated in endometrial epithelial tumour cells compared to endometrial epithelium from postmenopausal women." (PMID 20553623, 2010). "In all tissues, IL11 and IL11Rα immunoreactivity was mainly localised to epithelial cells of tumour origin." (PMID 20553623, 2010). "Furthermore, analysis of the GSE13507 dataset revealed that six genes, LIMS2, IRAK3, STX2, CYP27A1, IL11RA, and KCNMB1, had AUC values greater than 0.7, demonstrating good diagnostic potential in differentiating healthy adjacent tissues from tumor samples." (PMID 40755754, 2025). "IL‐11RA knockdown A549 tumour‐bearing mice exhibited a significant lower tumour burden." (PMID 40673604, 2025). "Notably, therapeutic targeting of IL‐11RA with a neutralising antibody demonstrated significant anti‐tumour efficacy in a PDX model." (PMID 40673604, 2025). "Indeed, patient tumor samples with low IL-11Rα expression also displayed low levels of c-MYC gene expression while samples with high IL-11Rα expression correlated with levels of c-MYC gene expression." (PMID 36834778, 2023). "We investigated the potential for IL11Rα inhibition to impair high grade tumour growth in vivo and determine whether it may enhance the efficacy of doxorubicin." (PMID 28186993, 2017). "We aimed to determine whether combination treatment using an anti-human IL11Rα blocking antibody (Ab) and doxorubicin chemotherapeutic impairs high grade tumour growth." (PMID 28186993, 2017). "We aimed to determine whether combination treatment using anti-human IL11Rα blocking antibody (Ab) and doxorubicin chemotherapeutic impairs high grade tumour growth." (PMID 28186993, 2017). "Very little immunoreactive IL11 and IL11Rα was seen in the stromal compartment of the tumours." (PMID 20553623, 2010). "The IL‐11/IL‐11RA axis emerges as a critical driver of LUAD tumourigenesis, exerting its effects through enhanced tumour cell proliferation and remodelling of the tumour microenvironment." (PMID 40673604, 2025). "To validate the expression levels of the eight key genes (LIMS2, TP53INP2, IRAK3, STX2, CYP27A1, IL11RA, KCNMB1, and PDLIM7) in tumor and non-tumor samples, we analyzed their expression in TCGA and GSE7476 datasets." (PMID 40755754, 2025). "Compared with our findings in Il11−/− mice and focus on IL11 regulation in tumor cell CXCL9 and MHC-I to increase CD8+ T infiltration, Huynh hinted a novel regulation besides IL11Ra for IL11 to exert immune suppression." (PMID 37365574, 2023). "Subcutaneous xenograft tumours were established in female Balb/c athymic nude mice using AN3CA cells expressing IL11 and IL11Rα." (PMID 28186993, 2017). "We recently demonstrated that an IL11Rα blocking Ab reduced Ishikawa and HEC1A cell proliferation, invasion and migration in vitro and also impaired tumour growth in vivo." (PMID 28186993, 2017). "IL11Rα blocking Ab reduced STAT3 phosphorylation and combination treatment with doxorubicin resulted in a significant reduction in tumour growth (p < 0.05) compared to Ab, doxorubicin, or IgG control." (PMID 28186993, 2017). "We recently demonstrated that IL11Rα inhibition reduces low and moderate G1-derived Ishikawa and G2-derived HEC1A endometrial xenograft tumour growth and metastasis in ectopic and orthotopic mouse models." (PMID 28186993, 2017). "Angiogenesis is also a key determinant of tumour formation and hence the localization of IL11 and IL11Rα to vascular smooth muscle and endothelial cells in the present study suggest a potential role in angiogenesis." (PMID 20553623, 2010). "Furthermore, qRT-PCR experiments showed that LIMS2, IRAK3, STX2, IL11RA, KCNMB1, and PDLM7 were significantly downregulated in the tumor group, consistent with the bioinformatic analysis results, suggesting their potential clinical value." (PMID 40755754, 2025).
tumor (continued). "Despite no reduction in tumour cell proliferation rate, IL11Rα Ab and doxorubicin combination treatment resulted in reduced xenograft tumour growth in vivo versus all other treatment groups." (PMID 28186993, 2017). "Expression levels of interleukin-13 (IL-13), leptin, lymphotoxin β receptor (LTbR), and macrophage inflammatory protein 1β (MTP1β) were significantly higher and expression level of IL-11Rα was lower for tumor-positive nodes as compared with tumor-negative SN." (PMID 24212647, 2011). "IL11Rα staining was higher in epithelial tumour cells in Grade 1 and 2 but not Grade 3 compared to endometrial epithelial cells from control postmenopausal women (p < 0.05)." (PMID 20553623, 2010). "Immunolocalization confirmed that AN3CA tumours produce IL11 and IL11Rα protein in the human-derived tumour epitheilial cells, suggesting the potential for recombinant human IL11 to signal via IL11Rα in the tumour epitheilium and to target the receptor using our anti-human IL11Rα blocking Ab." (PMID 28186993, 2017). "Therefore, we performed immunofluorescence staining with FITC-conjugated IL-11Rα-targeting peptides in combination with anti-CD4 or anti-CD8 antibodies, respectively, to reflect the co-localization of tumor-infiltrating T cells and tumor cells in the tumor tissues." (PMID 38067271, 2023). "IL11Rα Ab treatment did not alter IL11 mRNA, but led to a trend in increased GP130 mRNA, while IL11Rα Ab and doxorubicin treatment significantly increased IL11Rα (p < 0.05) in subcutaneous AN3CA tumours." (PMID 28186993, 2017).